STAG3L4 (STAG3 cohesin complex component like 4 (pseudogene))
Synonyms: FLJ13195; STAG3L4P
Gene: Transcribed unprocessed pseudogene on chromosome 7 (67,305,987 to 67,309,715, forward strand). Ensembl gene ENSG00000106610.
Diseases named in the same sentence as STAG3L4 in open-access papers:
STAG3L4 is named in the same sentence as 1 disease in open-access papers, as found by Europe PMC text mining. Sharing a sentence is not in itself a finding about the gene and the disease. The quoted sentences say what the papers report.
T-cell leukemia (1 paper, 2016). A malignant disease of the T-lymphocytes in the bone marrow, thymus, and/or blood. "Therefore, we asked if STAG3L4 and/or AUTS2 show aberrant expression patterns in T-cell leukemia." (PMID 27322685, 2016).